PFN1 (profilin 1)
Description:
Binds to actin and affects the structure of the cytoskeleton. At high concentrations, profilin prevents the polymerization of actin, whereas it enhances it at low concentrations. By binding to PIP2, it inhibits the formation of IP3 and DG. Inhibits androgen receptor (AR) and HTT aggregation and binding of G-actin is essential for its inhibition of AR.
Synonyms: ALS18; PDB7
Tractability: Small molecule: a structure with a bound ligand is known. PROTAC: UniProt records ubiquitination sites on it; ubiquitination databases record sites on it; its protein half-life has been measured.
Gene: Protein-coding gene on chromosome 17 (4,945,652 to 4,950,517, reverse strand). Ensembl gene ENSG00000108518.
Subcellular location: Cytoplasm, cytoskeleton
Subcellular location (Human Protein Atlas): Cytosol
Pathways (Reactome):
Signal Transduction: PCP/CE pathway; RHO GTPases Activate Formins
Developmental Biology: Signaling by ROBO receptors
Hemostasis: Platelet degranulation
Gene Ontology:
Molecular function: actin binding; actin monomer binding; adenyl-nucleotide exchange factor activity; cadherin binding; phosphatidylinositol-4,5-bisphosphate binding; phosphotyrosine residue binding; proline-rich region binding; protein binding; RNA binding; small GTPase binding
Biological process: actin cytoskeleton organization; negative regulation of actin filament bundle assembly; negative regulation of stress fiber assembly; positive regulation of actin filament polymerization; positive regulation of epithelial cell migration; positive regulation of ruffle assembly; protein stabilization; positive regulation of actin filament bundle assembly; regulation of actin filament polymerization; modification of postsynaptic actin cytoskeleton; modulation of chemical synaptic transmission; regulation of actin filament organization; synapse maturation
Cellular component: blood microparticle; cell cortex; cytoplasm; extracellular exosome; focal adhesion; membrane; nucleus; cytosol; cytoskeleton; glutamatergic synapse
Genetic constraint (gnomAD): Loss-of-function variants: 0 observed, 9.24 expected, observed/expected ratio (o/e) 0, 90% interval 0 to 0.32. That is too few expected variants to judge how well the gene tolerates losing a copy. Missense variants: 81 observed, 146.6 expected, observed/expected ratio (o/e) 0.55, 90% interval 0.46 to 0.67. Synonymous variants: 60 observed, 63.74 expected, observed/expected ratio (o/e) 0.94, 90% interval 0.76 to 1.17.
Gene-disease validity (ClinGen):
ClinGen rates the evidence that PFN1 causes each of these diseases.
amyotrophic lateral sclerosis type 18 (autosomal dominant): Definitive.
Homologues: Orthologues: chimpanzee PFN1 (100% identical), macaque PFN1 (100% identical), mouse Pfn1 (96% identical), pig PFN1 (96% identical), guinea pig PFN1 (94% identical), rabbit PFN1 (68% identical). Paralogues in human: PFN2 (59% identical), PFN3 (43% identical).
Diseases named in the same sentence as PFN1 in open-access papers:
PFN1 is named in the same sentence as 128 diseases in open-access papers, as found by Europe PMC text mining. Sharing a sentence is not in itself a finding about the gene and the disease. The quoted sentences say what the papers report.
amyotrophic lateral sclerosis (36 papers, 2015 to 2025). Amyotrophic lateral sclerosis (ALS) is a neurodegenerative disease characterized by progressive muscular paralysis reflecting degeneration of motor neurons in the primary motor cortex, corticospinal tracts, brainstem and spinal cord. "Previously, mutations in the PFN1 gene, particularly missense mutations, were identified in patients with amyotrophic lateral sclerosis (ALS), a late-onset neurodegenerative disorder caused by the death of motor neurons." (PMID 40458045, 2025). "PFN1 deletion or mutations have been linked to numerous neurodegenerative diseases, including amyotrophic lateral sclerosis (ALS)." (PMID 40409555, 2025). "Studies on mice with PFN1 mutations demonstrate that alterations in this protein function cause symptoms resembling amyotrophic lateral sclerosis in humans." (PMID 39769211, 2024). "PFN1 is a small actin-binding protein composed of 139 amino acid residues, mutations of which cause amyotrophic lateral sclerosis." (PMID 37543598, 2023). "Mutation in profilin 1 (PFN1) is a pivotal factor in the etiology of amyotrophic lateral sclerosis (ALS), although the precise mechanisms of motor neuron degeneration in this context remain elusive." (PMID 37817804, 2023). "Some studies have also shown that PFN1 mutations can lead to amyotrophic lateral sclerosis (amyotrophic lateral sclerosis, ALS) through different mechanisms." (PMID 36291059, 2022). "It is of interest that previously, mutations of PFN1 had been identified by other investigators as a cause of amyotrophic lateral sclerosis (ALS) and that when the abnormal proteins were studied in vitro, insoluble protein aggregates were formed." (PMID 33988819, 2021). "Notably, PFN1 was a central protein for MSA total synuclein; PFN1 is strongly implicated in several neurodegenerative diseases, including amyotrophic lateral sclerosis, frontal temporal dementia, and motor neuron disease." (PMID 40122840, 2025). "PFN1 deletion or mutations can disrupt normal physiological activities and cause many neurodegenerative diseases, for example, mutations in the PFN1 protein have been linked to the development of amyotrophic lateral sclerosis (ALS)." (PMID 40409555, 2025). "Mutations in profilin 1 led to familiar amyotrophic lateral sclerosis." (PMID 33163494, 2020). "The recent identification of several mutations in PFN1, a protein involved in actin dynamics, strengthens the hypothesis that pathology of amyotrophic lateral sclerosis is linked to cytoskeletal defects." (PMID 26572741, 2015). "Impaired actin binding is a common denominator of several PFN1 mutations associated with amyotrophic lateral sclerosis, although further mechanisms may also contribute to the death of motor neurons." (PMID 26572741, 2015). "In amyotrophic lateral sclerosis (ALS), mutations of the gene of profilin (PFN1), the actin-binding protein that accelerates enzymatically the actin nucleotide exchange, have been identified as one of the genetic causes for the disease." (PMID 40328105, 2025). "In the context of amyotrophic lateral sclerosis (ALS), PFN1 mutations impair autophagy and mitochondrial integrity." (PMID 40981267, 2025). "Mutations in profilin 1 (PFN1) have been identified in rare familial cases of Amyotrophic Lateral Sclerosis (ALS)." (PMID 35628504, 2022). "Amyotrophic lateral sclerosis (ALS) is a major neurodegenerative disease, which is caused by mutated Pfn1 alleles." (PMID 34458253, 2021). "Recently, several Pfn1 mutations (C71G, M114T, E117G and G118V) have been linked to pathogenesis of familial Amyotrophic Lateral Sclerosis (ALS)." (PMID 27228149, 2016). "Interestingly, mutations in PFN1 (C71G, T109M, M114T, E117G, G118V, etc.)are associated with amyotrophic lateral sclerosis (ALS), a neurodegenerative disorder affecting motor neurons." (PMID 40458045, 2025).
amyotrophic lateral sclerosis (continued). "IL-1β deletion altered the expression of genes involved in extracellular region, including upregulation of PFN1 gene related to amyotrophic lateral sclerosis and increased the expression of the opposite strand of IL-1β." (PMID 37971544, 2024). "Among the more than sixty identified genes related to amyotrophic lateral sclerosis (ALS), there are eight encoded key cytoskeletal proteins, including ALS2 and PFN1." (PMID 37443816, 2023). "Recent findings link PFN1 to neurological diseases such as amyotrophic lateral sclerosis and Huntington’s disease." (PMID 36561122, 2022). "It has been recently reported that the subcellular localization of PFN1 is regulated by exportin 6 and amyotrophic lateral sclerosis(ALS)-related PFN1 mutations have cytoplasmic inclusions and decrease of nuclear import suggesting a critical role of nuclear compartment of PFN1." (PMID 33590416, 2021). "Profilin-1 imbalance has been found to be related to the occurrence and progression of amyotrophic lateral sclerosis, atherosclerosis, hypertension, and tumors." (PMID 34234838, 2021). "Thus far, eight DNA mutations in the PFN1 gene encoding the PFN1 protein are associated with human amyotrophic lateral sclerosis (ALS)." (PMID 30166578, 2018). "Finally, we will discuss recent findings that link PFN1 and PFN2a to neurological diseases, such as amyotrophic lateral sclerosis (ALS), Fragile X syndrome (FXS), Huntington’s disease and spinal muscular atrophy (SMA)." (PMID 34458253, 2021). "On the other hand, PFN1 (Profilin) gene was reported to be involved in amyotrophic lateral sclerosis (ALS)." (PMID 37971544, 2024). "Apart from mitochondria dysfunction associated with amyotrophic lateral sclerosis (ALS) linked mutants of PFN1, no current evidence indicates a direct connection between PFN1 and mitochondria." (PMID 39026010, 2024). "The identification of profilin 1 (PFN1) as a causative of familial amyotrophic lateral sclerosis (fALS) or sporadic ALS confirmed that the cytoskeletal pathway alterations are contributing to ALS pathogenesis." (PMID 32033020, 2020). "For instance, the potential effect of Riluzole and Edaravone, two FDA approved drugs for amyotrophic lateral sclerosis (ALS), that are known to play a key role in regards to the stabilization and structural deviations of the mutant profilin-1 gene (PFN-1) is assessed by in silico tools." (PMID 35962153, 2022). "Additionally, some cases of PDB-like syndromes have been attributed to mutations in VCP, TNFRSF11A, TNFRSF11B, HNRNPA2B1, HNRNPA1, ZNF687 and PFN1, most of which are known to involved in the amyotrophic lateral sclerosis (ALS) and nuclear factor kappa B (NF-kB) signaling pathways." (PMID 35355568, 2022). "Therefore, in the following we will focus on the roles of PFN1 and/or PFN2a in a subset of prominent neurological pathologies comprising Amyotrophic lateral sclerosis (ALS), Fragile X syndrome (FXS), Huntington’s disease (HD), and spinal muscular atrophy (SMA)." (PMID 34458253, 2021).
breast carcinoma (32 papers, 2005 to 2024). "In colorectal cancer and breast cancer, high profilin 1 expression was associated with lower stage and longer survival." (PMID 33163494, 2020). "First, we transiently overexpressed mCherry-actin along with either WT- or T89A- or T89D- variants of Pfn1 (all constructs were EGFP-fused) in MDA-MB-231 (MDA-231) breast cancer cells." (PMID 27228149, 2016). "Mutation affecting actin-binding ability (PFN-R74E) of profilin 1 enhanced its tumorigenic function whereas mutation affecting its poly-L-proline binding function (PFN-H133S) alleviated these mechanisms in breast cancer cells." (PMID 25084196, 2014). "We then studied the effects of overexpression of either functional or ligand-binding deficient mutants of Pfn1 on breast cancer cell motility." (PMID 17940506, 2007). "First, we demonstrate that near complete loss of Pfn1 expression actually confers increased motility and invasiveness to breast cancer cells." (PMID 17940506, 2007). "Related to this postulate, we first investigated how loss of Pfn1 expression affects the motility of breast cancer cells and normal human mammary epithelial cells (HMEC)." (PMID 17940506, 2007). "Since WASP-family proteins, Arp-2/3 as well as their upstream regulators (Rac1, Cdc42) are known to be overexpressed in several invasive cancers including breast cancer, protrusion of tumour cells may be much less sensitive to loss of Pfn1 expression compared to vascular endothelial cells." (PMID 17940506, 2007). "We particularly emphasize on SBSN and PFN1, as these proteins were observed to be progressively overexpressed and under expressed, respectively, in breast cancer samples compared to control samples, ranging from early-stage to metastatic cases." (PMID 39990193, 2024). "Profilin-1 (PFN1), an important actin regulatory protein, is downregulated in human breast cancer and has the ability to inhibit tumor initiation in triple-negative breast cancer cells." (PMID 38531846, 2024). "For example, PFN1 promotes the metastasis of breast cancer and hepatocellular carcinoma, while PFN1 inhibits the metastasis of bladder cancer." (PMID 35586060, 2022). "Accumulating evidence suggests that PFN1 participates in the metastasis of breast cancer, hepatocellular carcinoma, and renal cell cancer." (PMID 35586060, 2022). "In fact, depletion of PFN1 in breast cancer cells has enabled hyper-migratory phenotype in vitro and enhanced hematogenous dissemination from primary tumor in vivo." (PMID 34681026, 2021). "It has been previously reported that balanced levels of PFN1 is essentially required for the stemness of breast cancer cell, MB-231." (PMID 33590416, 2021). "In breast cancer, overexpression of PFN1 upregulates PTEN expression following decrease of levels in AKT activation and PFN1-PTEN interaction inhibits IKK phosphorylation leading to suppress NF-kB activation." (PMID 33590416, 2021). "Overexpression of Profilin-1 also has the ability to suppress the invasiveness and motility of breast cancer cells, which is a negative regulator of mammary carcinoma aggressiveness." (PMID 32079071, 2020). "Profilin-1 has been regarded as a tumour-suppressor molecule for breast cancer and the up-regulation of prifilin-1 after irradiation, induced apoptosis in pancreatic cancer cells." (PMID 30602943, 2018). "Previous documented findings demonstrated that augmented profilin 1 synthesis can increase PTEN gene expression in breast cancer cell." (PMID 26955879, 2016). "Studies in breast cancer, occasionally suggested PFN1 promoting tumor establishment or suppressing metastasis." (PMID 27683119, 2016). "Another recent report showed that PFN1 had contrasting effects on breast cancer in a context-dependent manner." (PMID 27188458, 2016).
breast carcinoma (continued). "This is in agreement with a study in breast cancer, supporting an emerging role of PFN1 in the early tumorigenesis." (PMID 27683119, 2016). "An over-expression of PFN1 suppresses micro-metastasis of MDA-MB-231 breast cancer cells in nude mice." (PMID 26576504, 2015). "Immunohistochemical analysis of human breast cancers revealed intermediate to low levels of profilin 1 expression." (PMID 25084196, 2014). "It has been shown that profilin 1 promotes membrane protrusion, cell migration and invasion while profilin 2 suppresses these processes in breast cancer." (PMID 25084196, 2014). "In this study we demonstrate for the first time that phosphorylation of profilin 1 at serine 137 enhances oncogenic properties in breast cancer cells." (PMID 25084196, 2014). "Profilin 1 has been extensively studied in breast cancer cell lines and mouse models for breast cancer." (PMID 25084196, 2014). "Studies supporting its role in cellular proliferation, migration and invasion in breast cancer differed suggesting a dichotomous role for profilin 1 in breast cancer progression thereby necessitating further studies in this area." (PMID 25084196, 2014). "Since profilin 1 levels were high in patients with breast cancer, we overexpressed profilin 1 and some of its mutants in MCF7 cells to study their effect on cancer progression." (PMID 25084196, 2014). "We found elevated profilin 1 (PFN) in human breast cancer tissues when compared to adjacent normal tissues." (PMID 25084196, 2014). "Studies presented here demonstrate that S137 phosphorylation of profilin 1 not only augment migration and invasion in breast cancer cells (MCF7) but also enable them to become anchorage independent." (PMID 25084196, 2014). "Our present data on human breast cancer tissues from Indian population revealed enhanced expression of profilin 1 when compared to adjacent normal tissues of the breast." (PMID 25084196, 2014). "Elevated protein levels of PKCζ in breast cancer tissues were indicative of a phosphorylation event targeting profilin 1 too." (PMID 25084196, 2014). "Overexpression of wild-type profilin 1 (PFN-WT) in breast cancer MCF7 cells made them more migratory, invasive and adherent independent in comparison to empty vector transfected cells." (PMID 25084196, 2014). "Profilin 1 levels were significantly higher in breast cancer tissues compared to their adjacent normal counterparts." (PMID 25084196, 2014). "In breast cancer and several other adenocarcinomas, Pfn-1 expression is downregulated when compared to normal tissues." (PMID 24520372, 2014). "Profilin 1 was found to be downregulated in breast cancer cells CAL51, in pancreatic cancer, and in hepatocarcinoma tissues and upregulated in gastric cancer." (PMID 25084196, 2014). "Breast cancer MDA-MB-231 cells showed reduced migration upon overexpression of profilin 1, however, an in depth analysis carried out by silencing profilin 1 showed suppressed endothelial cell proliferation, migration and cord morphogenesis." (PMID 25084196, 2014). "We then exploited the assay's imaging compatibility to identify compounds that perturb expression of Pfn-1 in breast cancer cells." (PMID 24520372, 2014). "Conversely, overexpression of Pfn-1 inhibits proliferation, migration, and invasion of breast cancer cells in vitro and suppresses tumor growth in vivo." (PMID 24520372, 2014). "Although profilin 1 inhibits migration in breast cancer cells, profilin 1 stimulates migration of HUVEC and mesenchymal stem cells and is enriched at the dynamic plasma membranes of migrating or spreading cells." (PMID 22359590, 2012). "As a tumor suppressor in breast cancer cells, PFN1 was reported to be involved in multiple cell behaviors, including cell adhesion, growth, proliferation and signal transduction." (PMID 20403181, 2010). "Expression of profilin-1 (Pfn1) is downregulated in breast cancer cells, the functional significance of which is yet to be understood." (PMID 17940506, 2007).